MAP3K5 (mitogen-activated protein kinase kinase kinase 5)
Description:
Serine/threonine kinase which acts as an essential component of the MAP kinase signal transduction pathway. Plays an important role in the cascades of cellular responses evoked by changes in the environment. Mediates signaling for determination of cell fate such as differentiation and survival. Plays a crucial role in the apoptosis signal transduction pathway through mitochondria-dependent caspase activation. MAP3K5/ASK1 is required for the innate immune response, which is essential for host defense against a wide range of pathogens. Mediates signal transduction of various stressors like oxidative stress as well as by receptor-mediated inflammatory signals, such as the tumor necrosis factor (TNF) or lipopolysaccharide (LPS). Once activated, acts as an upstream activator of the MKK/JNK signal transduction cascade and the p38 MAPK signal transduction cascade through the phosphorylation and activation of several MAP kinase kinases like MAP2K4/SEK1, MAP2K3/MKK3, MAP2K6/MKK6 and MAP2K7/MKK7. These MAP2Ks in turn activate p38 MAPKs and c-jun N-terminal kinases (JNKs). Both p38 MAPK and JNKs control the transcription factors activator protein-1 (AP-1).
Synonyms: ASK1; MAPKKK5; MEKK5
Tractability: Small molecule: a drug acting on it is in phase 2 or 3 trials; a structure with a bound ligand is known; a high-quality ligand is known; it has a high-quality binding pocket; it belongs to a druggable protein family. PROTAC: UniProt records ubiquitination sites on it; ubiquitination databases record sites on it; its protein half-life has been measured; a small molecule that binds it is known.
Target class: Enzyme; STE protein kinase STE11 family; Kinase; STE protein kinase group; Protein Kinase
Safety:
Unwanted effects reported when the protein is acted on. In parentheses: how it was acted on, where the effect was seen, and who reports it.
heart disease (cardiovascular system; source: Force et al. (2011))
Gene: Protein-coding gene on chromosome 6 (136,557,034 to 136,793,097, reverse strand). Ensembl gene ENSG00000197442.
Subcellular location: Cytoplasm; Endoplasmic reticulum
Subcellular location (Human Protein Atlas): Cytosol
Pathways (Reactome):
Cellular responses to stimuli: Oxidative Stress Induced Senescence
Gene Ontology:
Molecular function: ATP binding; identical protein binding; JUN kinase kinase kinase activity; magnesium ion binding; MAP kinase kinase kinase activity; protein binding; protein domain specific binding; protein homodimerization activity; protein kinase activity; protein phosphatase binding; protein serine kinase activity; protein serine/threonine kinase activity; protein kinase binding
Biological process: apoptotic signaling pathway; cellular response to amino acid starvation; cellular response to hydrogen peroxide; intrinsic apoptotic signaling pathway in response to oxidative stress; JNK cascade; MAPK cascade; neuron intrinsic apoptotic signaling pathway in response to oxidative stress; positive regulation of apoptotic process; positive regulation of DNA-templated transcription; positive regulation of JNK cascade; response to endoplasmic reticulum stress; stress-activated MAPK cascade; cellular senescence; intrinsic apoptotic signaling pathway in response to endoplasmic reticulum stress; neuron apoptotic process; p38MAPK cascade; positive regulation of myoblast differentiation
Cellular component: cytoplasm; cytosol; IRE1-TRAF2-ASK1 complex; protein kinase complex; protein-containing complex; endoplasmic reticulum
Genetic constraint (gnomAD): Loss-of-function variants: 34 observed, 104.51 expected, observed/expected ratio (o/e) 0.33, 90% interval 0.25 to 0.43. The upper end of that interval is the gene's LOEUF score, 0.43, which puts it in group 1 of 6, group 1 being the genes least tolerant of losing a copy. Missense variants: 949 observed, 1,268 expected, observed/expected ratio (o/e) 0.75, 90% interval 0.71 to 0.79. Synonymous variants: 447 observed, 464.19 expected, observed/expected ratio (o/e) 0.96, 90% interval 0.89 to 1.04.
Homologues: Orthologues: chimpanzee MAP3K5 (99% identical), macaque MAP3K5 (99% identical), dog MAP3K5 (96% identical), mouse Map3k5 (95% identical), rat Map3k5 (95% identical), pig MAP3K5 (93% identical), guinea pig MAP3K5 (92% identical), rabbit MAP3K5 (91% identical), tropical clawed frog map3k5 (75% identical), zebrafish map3k5 (72% identical), Drosophila melanogaster Ask1 (39% identical), Caenorhabditis elegans nsy-1 (38% identical). Paralogues in human: MAP3K15 (56% identical), MAP3K6 (44% identical).
Diseases named in the same sentence as MAP3K5 in open-access papers:
MAP3K5 is named in the same sentence as 223 diseases in open-access papers, as found by Europe PMC text mining. Sharing a sentence is not in itself a finding about the gene and the disease. The quoted sentences say what the papers report.
diabetes (29 papers, 2010 to 2025). "Hazard ratios (HR) by genotype of MAP3K5 SNP rs2076260 with total mortality in men with diabetes, CHD, hypertension, and any of these CMDs." (PMID 33739303, 2021). "For the kinase MAP3K5 it was hypertension, CHD and diabetes, for the kinase receptor PIK3R1 hypertension, CHD and stroke, and for the growth hormone receptor gene (GHR) and vascular endothelial growth factor receptor 1 gene (FLT1), it was nullifying the higher mortality risk posed by hypertension." (PMID 37561089, 2023). "For FOXO3, MAP3K5, PIK3R1, mitigation of pathological effects of other cardiovascular diseases and/or diabetes represent an additional means whereby individuals with longevity (resilience) genotypes can have a normal lifespan despite possessing one or more of these aging-related conditions." (PMID 37561089, 2023). "More importantly, key genes of the respective pathways, such as AKT3, FGF2, FGF7, mitogen-activated protein kinase 4 (MAP3K4), MAP3K5, insulin receptor (INSR), AKT3, and mTOR, were also enriched in the analysis, thus explaining the link between diabetes and BCRL subjects in the present study." (PMID 36232660, 2022).
breast carcinoma (23 papers, 2012 to 2024). "(D) Relative mRNA expression of MAP3K5 in different breast cancer subtypes from the METABRIC cohort (n=1700)." (PMID 32357907, 2020). "Although known to be associated with other cancer types, to our knowledge, MAP3K5 has not been implicated in breast cancer." (PMID 32357907, 2020). "Similar to expression of pS134-GR and 14-3-3ζ (above), MAP3K5 mRNA levels are elevated in TNBC relative to other breast cancer subtypes represented in the METABRIC, and MAP3K5 and GR mRNA expression levels are strongly correlated in TNBC patients." (PMID 32357907, 2020).
cardiac hypertrophy (23 papers, 2009 to 2026). "ASK1 also plays roles in negatively regulating physiologic cardiac remodeling as Map3k5−/− mice developed more pronounced cardiac hypertrophy in response to swimming that was associated with increased cardiac Akt signaling and impaired p38 MAPK activation." (PMID 41333012, 2025).
pancreatic cancer (20 papers, 2011 to 2025). "MAP3K5 is a serine/threonine kinase that mediates the MAP kinase signal transduction pathway in different cancer types, such as pancreatic cancer, prostate cancer, and thyroid cancer." (PMID 37285835, 2023).
Insulin resistance (19 papers, 2014 to 2025). Increased resistance towards insulin, that is, diminished effectiveness of insulin in reducing blood glucose levels. "The MAP3K5 gene was upregulated in adipose tissues of obese animal, and a MAP3K5 mutation that decreased RNA expression was linked to obesity with whole body insulin resistance." (PMID 34262592, 2021).
osteosarcoma (19 papers, 2013 to 2025). A usually aggressive malignant bone-forming mesenchymal neoplasm, predominantly affecting adolescents and young adults. "A study that identified four genes predicting the survival of osteosarcoma patients showed that MAP3K5 is negatively correlated with survival risk and risk score, which is consistent with our results." (PMID 36899330, 2023). "MAP3K5 is a macrophage-associated gene signature member to predict the prognosis of osteosarcoma and might direct immunotherapy." (PMID 36899330, 2023). "In the present study, we analyzed the high-throughput RNA-sequencing data and clinical information of 86 osteosarcoma patients, and identified eight prognosis-related genes, including MAP3K5, G6PD, HMOX1, ATF4, ACADVL, MAPK1, MAPK10, and INS." (PMID 37285835, 2023). "Five ferroptosis-associated genes (MUC1, MAP3K5, LURAP1L, HMOX1, and BNIP3) correlated with the prognosis of osteosarcoma were screened for the construction of the risk score model." (PMID 36899330, 2023). "The selected 5 MAGs (MAP3K5, PML, WDR1, BAMBI, and GNPDA2) were identified as prognostic-related genes for osteosarcoma, and a novel macrophage-associated risk model was constructed based on these 5 MAGs." (PMID 34188683, 2021). "In general, 5 MAGs (MAP3K5, PML, WDR1, BAMBI, and GNPDA2) correlated with the prognosis of osteosarcoma were screened for the construction of the risk model." (PMID 34188683, 2021). "Accordingly, in osteosarcoma, TUBB and MAP3K5 were believed to function as tumor suppressors, actively inhibiting tumor growth and progression, while TERT and PPARG appear to act as cancer promoters, exacerbating the development of osteosarcoma." (PMID 39980969, 2024). "Among the five DE-ERSRGs, the Kaplan–Meier survival analysis suggested that osteosarcoma patients exhibiting high expression levels of BCL2, MAGEA3, MAP3K5, and TXNDC12 had significantly improved overall survival rates." (PMID 38229155, 2024). "MAP3K5, LURAP1L, HMOX1 and BNIP3 expression levels were markedly decreased in the osteosarcoma cells compared with the normal human osteoblast hFOB1.19 cells, they are negatively related with the riskscore." (PMID 36899330, 2023). "The expression of gene WDR1 (p = 0.006), PML (p = 0.005), MAP3K5 (p = 0.010), and GNPDA2 (p = 0.009) were significantly higher in normal bone sample while in osteosarcoma samples, the expression of BAMBI (p = 0.006) was significantly higher." (PMID 34188683, 2021). "Gene WDR1 (p = 0.003), PML (p = 0.002), MAP3K5 (p < 0.001), and GNPDA2 (p = 0.030) showed a better prognosis of osteosarcoma in the high expression group." (PMID 34188683, 2021). "MAP3K5, LURAP1L, HMOX1 might serve as negative risk factor for prognosis of osteosarcoma or melanoma." (PMID 36899330, 2023).
gastric cancer (18 papers, 2012 to 2024). A primary or metastatic malignant neoplasm involving the stomach. "Expression of MAP3K6 is variable in many human tumors, with expression most significantly reduced in gastric cancer tumors compared to healthy gastric tissue, whereas MAP3K5 expression is increased." (PMID 25340522, 2014). "Indeed MAP3K5−/− mice are more resistant to chemically induced gastric cancers than wild-type mice." (PMID 25340522, 2014).
melanoma (15 papers, 2012 to 2025). A malignant, usually aggressive tumor composed of atypical, neoplastic melanocytes. "The MAP3K5 R256C mutation identified in ctDNA and melanoma gDNA from patient 10 has also been identified in melanoma, and shown to inhibit the pro-death activity of this kinase." (PMID 31795494, 2019). "Frequent somatic mutations in MAP3Ks, including MAP3K5 and MAP3K9, were identified in melanoma patients." (PMID 37692064, 2023). "There have been several studies that have investigated the role of somatic mutations in MAP2K1 and MAP2K2, and in MAP3K5 and MAP3K9 in melanoma." (PMID 37504268, 2023). "The nearly significant TDP52L is a regulator of MAP3K5 protein kinase and has been shown to be involved in cell proliferation of melanoma cells." (PMID 35269844, 2022). "As expected, this list included well documented frequent oncogenic drivers of melanoma, including hotspot mutations in BRAF, NRAS, RAC1, PPP6C, TRRAP, MAP3K5 and BCL2L12." (PMID 24913145, 2014). "Mutations and the loss of heterozygosity of MAP3K5 and MAP3K9 in 85% and 67% of melanoma samples, respectively, suggest inactivation of these kinases." (PMID 24743024, 2014). "Some studies have also shown that targeting MAP2K1 and MAP2K2, and MAP3K5 and MAP3K9 with specific drugs can be effective at inhibiting the growth of melanoma cells in preclinical models." (PMID 37504268, 2023). "Presence of mutations in three functional components of RAC pathways (Rho family proteins, MAP3K5 and MAP3K9, PREX2) strongly indicates involvement of RAC pathway in pathogenesis of melanoma." (PMID 24743024, 2014).
Obesity (15 papers, 2014 to 2023). Accumulation of substantial excess body fat. "MAP3K5/ASK1 may influence in vivo insulin action and obesity, and MAP3K5 variants are associated with type 2 diabetes." (PMID 33739303, 2021).
prostate carcinoma (12 papers, 2009 to 2023). A carcinoma that arises from epithelial cells of the prostate gland. "MAP3K5 is known to be involved in tumorigenesis and inflammatory processes and its expression is elevated in high-risk prostate cancer, consistent with our observations." (PMID 37534375, 2023). "A somatic mutation resulting in the loss of 333 bp within the coding region of MAP3K5, a gene previously shown to be differentially expressed in prostate cancer, was also observed." (PMID 28423598, 2017). "We predicted oncogenic potential for a 333 bp deletion causing a frameshift in the apoptotic gene MAP3K5, previously shown to be differentially expressed in prostate cancer." (PMID 28423598, 2017). "Closely associated MAP3K5 has been studied to have similar role also in prostate cancer." (PMID 36809527, 2023). "A MAP3K5 mutation is related to malignant stages of prostate cancer." (PMID 33036415, 2020). "The genes MAP3K5 and PDIA3 are associated with malignant stages of prostate cancer and therefore provide novel potential biomarkers." (PMID 20035634, 2009). "MAP3K5 and PDIA3 were also identified in other prostate cancer profiling studies." (PMID 20035634, 2009).
lung carcinoma (9 papers, 2015 to 2024). "In details, MAP3K5, also known as ASK1, is involved in the ASK1-p38 axis and activated by lipid ROS accumulation, implementing ferroptosis in lung cancer cells." (PMID 34284753, 2021).
myocardial infarction (9 papers, 2018 to 2026). Gross necrosis of the myocardium, as a result of interruption of the blood supply to the area, as in coronary thrombosis. "Global loss of ASK1 in Map3k5−/− mice resulted in no basal cardiac phenotype but improved function, reduced ventricular dilation, and reduced cardiomyocyte apoptosis following myocardial infarction or pressure overload and reduced hypertrophy following AngII infusion." (PMID 41333012, 2025).
Alzheimer disease (8 papers, 2007 to 2023). A progressive, neurodegenerative disease characterized by loss of function and death of nerve cells in several areas of the brain leading to loss of cognitive function such as memory and language. "Additionally, AST4 expressed a high level of MAP3K5, MAPK10, and TUBB3, which are enriched in Alzheimer's disease–related pathways (hsa05010, P = 2.0 × 10−07)." (PMID 38091510, 2022).
viral infection (8 papers, 2010 to 2025). "Similarly, MAP3K5 up-regulation may be a reaction to viral infection as this protein is thought to be associated with apoptotic death." (PMID 21067549, 2010). "The result of ChIP-PCR showed that FB-tagged NR2F6 did not bind MAP3K5 without virus infection, and was recruited to MAP3K5 promoter region upon HSV-1 treatment." (PMID 38829910, 2024).
colon cancer (7 papers, 2014 to 2021). "Furthermore, knockout MAP3K5 mice were more likely to develop colon cancer." (PMID 34188683, 2021).
Hypertension (6 papers, 2020 to 2026). The presence of chronic increased pressure in the systemic arterial system. "In studies of FOXO3, MAP3K5, PIK3R1, GHR, and FLT1 we found that for each, the genetic variants associated with longer lifespan may activate cell resilience mechanisms, leading to amelioration of the adverse effects of hypertension." (PMID 37561089, 2023). "Besides, longevity-promoting resilience genes like FLT1, Foxo3, GHR3, MAP3K5, PIK3R1 could mitigate mortality from hypertension, which further indicating the genetic influences in hypertension and vascular aging." (PMID 41507140, 2026).
non-alcoholic fatty liver disease (6 papers, 2019 to 2024). "Six of the key metagenes—INSR, MAP3K5, NDUFB8, NDUFS1, SDHB, and UQCRC2—are involved in nonalcoholic fatty liver disease (hsa04932), which is caused by a defect in insulin suppression of free fatty acid (FAA) disposal due to the induction of insulin resistance." (PMID 36979367, 2023).
osteoporosis (6 papers, 2017 to 2024). A condition of reduced bone mass, with decreased cortical thickness and a decrease in the number and size of the trabeculae of cancellous bone (but normal chemical composition), resulting in increased fracture incidence. "Compared with the control group, HIST1H3G, NOP2, OXA1L, and ZFPM2 were upregulated in osteoporosis, and MAP3K5 was downregulated." (PMID 33778083, 2021).
epilepsy (5 papers, 2018 to 2025). A brain disorder characterized by episodes of abnormally increased neuronal discharge resulting in transient episodes of sensory or motor neurological dysfunction, or psychic dysfunction. "Therefore, MAP3K5 seems a good candidate for explaining the mechanisms underpinning intellectual disability and epilepsy." (PMID 29739397, 2018).
Sepsis (5 papers, 2021 to 2024). Sepsis is defined as life-threatening organ dysfunction caused by a dysregulated host response to infection. "MAP3K5 was also identified as one of the ferroptosis-related genes in sepsis by bioinformatics analysis." (PMID 36837498, 2023). "The results indicated that 8 genes (MAPK14, MAPK8, TLR4, MAP3K5, CYBB, DUSP1, MAPK1 and ATM) might be closely related to the occurrence of sepsis." (PMID 36117534, 2022).
autoimmune disease (3 papers, 2020 to 2021). A disorder resulting from loss of function or tissue destruction of an organ or multiple organs, arising from humoral or cellular immune responses of the individual to their own tissue constituents. "MAP3K5 (also named ASK1), which was the hub gene in turquoise module acquired from WGCNA, is an important member of mitogen-activated protein kinase (MAPK) family and plays crucial roles in physiological processes associated with autoimmune diseases." (PMID 34615554, 2021).
colitis (3 papers, 2020 to 2023). Inflammation of the colon. "The involvement of MAPKs in the favorable effects of nicotine on DSS-induced colitis was also highlighted by the inferred downregulation of Map3k5 that would, according to the IBD model, decrease translocation of Ocln and Tjp1 from tight junctions to the cell membrane." (PMID 37047398, 2023).
thyroid cancer (3 papers, 2016 to 2023). "AKR1C3, BID, FBXW7, GPX4, and MAP3K5 were independent prognosis signatures of thyroid cancer." (PMID 35741758, 2022). "In previous studies, BID, FBXW7, and GPX4 had already been found to be significant in thyroid cancer, whereas the role of AKR1C3 and MAP3K5 in the development and progression of thyroid cancer has not yet been reported." (PMID 35741758, 2022).
endometriosis (2 papers, 2022). The growth of functional endometrial tissue in anatomic sites outside the uterine body. "The upregulated expression of MAP3K5 and KPNB1 suggests that they may be involved in the apoptosis of GCs, which is consistent with the study that GCs from patients with endometriosis show increased levels of apoptosis." (PMID 35295989, 2022).